ANXA6 (annexin A6)
Diseases named in the same sentence as ANXA6 in open-access papers (continued):
Sharing a sentence is not in itself a finding about the gene and the disease.
breast carcinoma (continued). "We demonstrate that in invasive BT-549 breast cancer cells AnxA6 expression is required for sustained membrane localization of activated (phosho-Y1068) EGFR and consequently, persistent activation of MAP kinase ERK1/2 and phosphoinositide 3-kinase/Akt pathways." (PMID 24354805, 2013). "We provide evidence suggesting that reduced AnxA6 expression is significantly associated with higher recurrence-free but lower distant metastasis-free (DMFS) and overall survival of patients with basal-like breast cancer." (PMID 24354805, 2013). "This is based on a number of reports that have amply demonstrated that over expression of the protein in the non-invasive A431 epidermoid carcinoma cells as well as BT20 and MDA-MB-468 breast cancer cells that either lack, or express low levels of AnxA6 inhibited their growth." (PMID 24354805, 2013). "Together these data confirm the variable response of breast cancer cells to EGFR targeted therapies suggest that reduced AnxA6 expression may be more relevant in breast cancer subtypes such as EGFR expressing invasive basal-like breast cancer." (PMID 24354805, 2013). "Moreover, cytotoxic drugs for breast cancer, such as taxanes and anthracyclines, could trigger the release of ANXA6-rich extracellular vesicles (ANXA6-EVs) from cancer cells, which promote tumor migration and invasion." (PMID 37129645, 2023). "ANXA6 expression has been reported to be upregulated in cancers such as pancreatic cancer, ovarian cancer, female thyroid cancer, and esophageal adenocarcinoma, but downregulated in hepatocellular carcinoma, gastric cancer, breast cancer, cervical cancer and triple negative breast cancer (TNBC)." (PMID 36936694, 2023). "After ANXA6-carrying exosomes were transported to the lungs through blood circulation, they promoted the expression of chemokines in lung tissues and recruited mononuclear macrophages, which were the “agent provocateurs” that helped lung metastasis of breast cancer." (PMID 35719975, 2022). "We hypothesized that interactions between members of the annexin family and FetuA should prevent osteoblast-mediated mineralization, similarly as in the case of interactions of FetuA with AnxA2 in VSMCs as well as or with AnxA2 and AnxA6 in breast carcinoma cells." (PMID 33924370, 2021). "Although considered to be constitutively expressed in most cell types, AnxA6 expression is also inducible by treatment of tumor cells with a variety of pharmacological drugs, and it is differentially expressed in various stages/subtypes of several cancer types including breast cancer." (PMID 32784650, 2020). "Finally, we will discuss the novel concept of therapy-induced upregulation of AnxA6 especially in basal-like TNBC cells with low AnxA6 levels (AnxA6-low TNBC cells) as another mechanism for acquired resistance of this hard-to-treat breast cancer subtype to TKIs." (PMID 32784650, 2020). "While reduced expression of AnxA6 enhances cell proliferation lack of or reduced expression of the protein has been shown to be associated with a decrease in the migration of invasive breast cancer cells (BCCs) and chick cranial crest cells." (PMID 24354805, 2013). "Moreover, the association of ANXA6 with H-Ras-containing protein complexes may contribute to the regulation of EGFR overexpression and p120GAP/Ras assembly in ER (−) breast cancer cells, thereby inhibiting Ras signaling in breast cancer cells." (PMID 37129645, 2023). "In breast cancer, studies have proven that ANXA2, ANXA4, ANXA5, ANXA6, and ANXA7 are required for repair in breast cancer cells, indicating that a network of annexins participate in the plasma membrane repair response." (PMID 34484309, 2021). "Tumor-derived and AnxA6-enriched EVs have also been shown to be prometastatic in mouse mammary tumor virus-polyoma middle tumor-antigen (MMTV-PyMT) and 4T1 mouse models of breast cancer." (PMID 32784650, 2020).
breast carcinoma (continued). "This phenotype is also consistent with our previous findings that low AnxA6 expression was associated with poor distant metastasis-free and overall survival of basal-like breast cancer patients and not those with other molecular subtypes or breast cancer patients in general." (PMID 30719209, 2019). "ANXA6 is downregulated in many EGFR (+) and estrogen receptor (ER) (–) breast cancer cells." (PMID 37129645, 2023). "Continuous chemotherapy pressure-elicited annexin-A6 (ANXA6)-containing exosome (ANXA6-exo) secretion contributes to paclitaxel (PTX) resistance in breast cancer (BC), but the molecular mechanisms are not fully elucidated." (PMID 34676207, 2021). "On the contrary, up-regulation of AnxA6 in the basal-like HCC1806 cells and MDA-MB-468 cells resulted in a decrease in RasGRF2 expression and this was also confirmed in 11 basal-like breast cancer cell lines at the mRNA level." (PMID 30719209, 2019). "It is also possible that the relatively modest EGFR prognostic value in some cancers including breast cancer, may be due to the modulation of its cellular levels and activity by amongst other cellular factors scaffolding proteins such as MUC4 and AnxA6." (PMID 24354805, 2013). "When these chemotherapy-induced ANXA6+ EV were injected into the tail vein of mice, they activated endothelial cells to produce the chemokine Ccl2, which led to the expansion of Ly6C+CCR2+ lung monocytes and thus pre-conditioned the lungs for the seeding of breast cancer metastases." (PMID 32731639, 2020). "Moreover, PTX-elicited extracellular vesicles contain high amount of annexin A6 (ANXA6), a Ca2+-binding protein, which can promote increased CCL2 expression in endothelial cells and consequent recruitment of inflammatory monocytes expressing CCR2, thereby promoting lung metastasis in breast cancer." (PMID 35280672, 2022). "Paclitaxel not only promoted the production of more exosomes in cancer cells, but also promoted the entry of annexin A6 (ANXA6) protein, a non-glycosylated polypeptide chain into exosomes by increasing calcium levels in cancer cells, which contributed to paclitaxel resistance in breast cancer." (PMID 35719975, 2022). "Immunohistochemical staining of breast cancer tissues revealed that compared to non-TNBC tumors, TNBC tumors express lower levels of AnxA6 and higher Ki67 expression." (PMID 32298357, 2020). "Likewise, the comparison of estrogen-receptor (ER) negative breast cancer cell lines with high (MDA-MB-436) and low (MDA-MB-468) AnxA6 levels showed a 55.0% reduction in the number of caveolae in the ER-negative cells with high AnxA6 expression levels." (PMID 17822395, 2007).
gastric cancer (17 papers, 2015 to 2025). A primary or metastatic malignant neoplasm involving the stomach. "Annexin A6 in extracellular vesicles from cancer-associated fibroblasts (CAFs) is transferred into gastric cancer cells, where it stabilizes β1 integrin at the gastric cancer cell surface." (PMID 40243917, 2025). "ANXA6 is downregulated by promoter methylation in gastric cancer and overexpression of ANXA6 inhibits gastric cell proliferation." (PMID 37129645, 2023). "For instance, ANXA2 directs the interaction of the protein YES1 and involves the EphA2-YES1-ANXA2 pathway, which promotes gastric cancer progression and metastasis, while ANXA6 suppresses gastric cancer progression by inhibiting Ras/MAPK signalling." (PMID 36936694, 2023). "Conversely, ANXA6 expression is negatively correlated with melanoma, gastric cancer, and chronic myeloid leukaemia disease progression." (PMID 36765657, 2023). "In contrast, ANXA6 expression is downregulated in primary gastric cancer tissues and directly inactivates the Ras/MAPK signalling pathway to inhibit gastric cancer growth." (PMID 36936694, 2023). "ANXA6 can promote network formation and drug resistance of gastric cancer cells by activating FAK-YAP signaling in the extracellular matrix." (PMID 37129645, 2023). "UNC5B is known to inhibit cell proliferation by inducing cell cycle arrest, and ANXA6 has been reported to induce cell cycle arrest in gastric cancer." (PMID 35457039, 2022). "Meanwhile, in breast, gastric cancer, hepatocellular and several other cancer types, elevated AnxA6 expression has also been reported to inhibit tumor cell proliferation." (PMID 32784650, 2020). "Annexin A6 functions as a tumor suppressor in gastric cancer cells through the inhibition of Ras/MAPK signaling." (PMID 25948494, 2015). "In gastric cancer, AnxA6 conferred drug resistance via β1 integrin and FAK activation." (PMID 35806209, 2022). "It was also reported that annexin A6, which is not expressed in gastric cancer cells, is expressed in involved cancer-associated fibroblasts, and gastric cancer cells acquire treatment resistance." (PMID 34283052, 2021). "Anxa6 expression was also inhibited in gastric cancer cells." (PMID 27699085, 2016). "Similarly, AnxA6 mRNA is down-regulated through promoter methylation in gastric cancer." (PMID 38566133, 2024). "Of note, this also appears to include extracellular AnxA6 activities in TNBC, PDAC and gastric cancer, affecting focal adhesion dynamics, metastatic behavior and response to therapy." (PMID 35806209, 2022). "ANXA6 is down-regulated in many cancers, and acts as cancer suppressor, which include highly aggressive triple-negative breast cancer (TNBC) subtypes, gastric cancer, cervical cancer, and hepatocellular carcinoma, bladder cancer." (PMID 37129645, 2023).
pancreatic cancer (16 papers, 2017 to 2026). "Increased expression of ANXA6 is associated with more advanced disease stages in cervical cancer and pancreatic cancer." (PMID 36765657, 2023). "Cell surface CD9 also can mediate the aggressiveness of pancreatic tumor cell interactions with annexin A6+ (ANXA6+) EVs." (PMID 38660297, 2024). "These EVs secreted by CAFs, especially those carrying CD9 and ANXA6 on their surface, are taken up by pancreatic cancer cells, subsequently activating the p38 MAPK signaling pathway, leading to increased EMT of the tumor cells." (PMID 38954230, 2024). "The exosomal transfer of ANXA6 was found to facilitate pancreatic cancer aggressiveness by the formation of the annexin A6/LDL receptor-related protein 1/thrombospondin 1 (ANXA6/LRP1/TSP1) complex." (PMID 39684264, 2024). "This includes studies showing that the upregulation of AnxA6 is an indicator of the progression of ovarian carcinomas, women’s thyroid cancer, polycystic ovarian syndrome, pancreatic cancer and esophageal adenocarcinoma." (PMID 32784650, 2020). "ANXA6+ (Annexin 6/LDL receptor-related protein-1/thrombospondin-1 complex) CAFs-secreted EVs enhanced tumor cell aggressiveness in pancreatic cancer." (PMID 32258040, 2020). "CAFs in pancreatic cancer form annexin A6/LDL receptor-related protein 1/thrombospondin 1 (ANXA6/LRP1/TSP1) complex, which is released in the form of extracellular vesicles (EVs), thereby enhancing the migratory capacity of cancer cells, which ingests EVs." (PMID 33050237, 2020). "In pancreatic cancer, cell aggressiveness characterized by an increase in proliferation and metastasis is dependent on the uptake of annexin A6 (ANXA6) positive CAF-derived exosomes." (PMID 32957712, 2020). "In pancreatic cancer, annexin A6 (ANXA6) was detected in high levels in CAF-derived sEVs." (PMID 39684264, 2024). "The detection of ANXA6 may be useful as a serum biomarker for esophageal adenocarcinoma and pancreatic cancer." (PMID 34238922, 2021). "However, the notion that tumor cell motility and invasiveness may be mediated by AnxA6-enriched EVs has now been independently demonstrated in breast and pancreatic cancers." (PMID 32784650, 2020). "Also, increased pancreatic cancer aggressiveness was shown to be dependent on tumor cell-mediated uptake of CAF-derived Annexin A6+ (ANXA6) EVs, and while depletion of ANXA6 in CAFs impaired pancreatic tumor and metastasis occurrence, injection of CAF-derived ANXA6+ EVs enhanced tumorigenesis." (PMID 28848498, 2017). "Specific membrane proteins such as CD151 and Netrin-1, along with the ANXA6/LRP1/TSP1 complex, further enhance the invasiveness and migration capabilities of pancreatic cancer cells by participating in cell–cell interactions and signaling transduction." (PMID 38954230, 2024).
cervical cancer (11 papers, 2018 to 2023). A primary or metastatic malignant neoplasm involving the cervix. "ANXA6 is correlated with microtubule-associated protein 1 light chain 3 in cervical cancer and inhibits tumorigenesis through autophagy induction." (PMID 36712880, 2022). "It has been used as a potential marker for cervical cancer, as several studies have shown the association of ANXA6 with the progression and malignancy of cervical cancer." (PMID 33135350, 2020). "Functionally, ANXA6 expression is correlated with LC3 (microtubule‐associated protein 1 light chain 3) expression in cervical cancer and ANXA6 inhibits tumourigenesis through autophagy induction." (PMID 33135350, 2020). "In cervical cancer, ANXA6 was downregulated and low levels of ANXA6 were associated with poor survival of cervical cancer patients, indicating that it serves as a tumor suppressor." (PMID 33135350, 2020). "ANXA6 displays tumor suppressor effects and ectopic expression of ANXA6 limits the growth of cervical cancer through autophagy induction; thus, their association contributes to cervical carcinogenesis." (PMID 33135350, 2020). "We also showed that ANXA6 correlates with autophagy levels and is downregulated in cervical cancer, while high levels of ANXA6 are associated with improved survival." (PMID 33135350, 2020). "Functionally, ANXA6 expression is correlated with LC3 (microtubule‐associated protein 1 light chain 3) expression in cervical cancer, and ANXA6 inhibits tumorigenesis through autophagy induction." (PMID 33135350, 2020). "In addition, data from the TIMER (Tumour Immune Estimation Resource) showed that low ANXA6 mRNA expression in cervical cancer was significantly associated with poor survival." (PMID 33135350, 2020). "Using the Oncomine database, we first analyzed ANXA6 mRNA levels in tissue samples from 45 cervical cancer patients and found that it was significantly downregulated in tumor tissues." (PMID 33135350, 2020). "IHC analysis showed that ANXA6 was lowly expressed in human cervical cancer tissues, indicating its tumor suppressive effect." (PMID 33135350, 2020). "Next, we conducted IHC analysis of ANXA6 protein levels in 100 human cervical cancer patients from Shanghai Putuo District People's Hospital." (PMID 33135350, 2020). "Here, we identified a newly synthesized protein, ANXA6, in starvation‐induced autophagy in cervical cancer cells." (PMID 33135350, 2020). "The possibility of enhancing ANXA6 levels as a cancer treatment is particularly interesting, as ANXA6‐mediated autophagic mechanisms display efficacy in a human cervical cancer xenograft model." (PMID 33135350, 2020). "Functionally, ANXA6‐induced autophagy serves as cell death and enhancing autophagy leads to cervical cancer suppression." (PMID 33135350, 2020). "In contrast, ANXA6 has been suggested to be a tumor promoter in cervical cancer, large cell lymphoma and the stroma of pancreatic ductal adenocarcinoma." (PMID 29849941, 2018). "On the other hand, ANXA6 is downregulated in cervical cancer, and elevated ANXA6 expression may induce autophagy-related signaling to inhibit cervical cancer tumorigenesis." (PMID 37129645, 2023). "Autophagy may influence the occurrence and metastasis of tumors and regulate metabolism and homeostasis in the body; it has been reported that ANXA6 induces autophagy in cervical cancer." (PMID 37138336, 2023). "ANXA6 suppressed the tumorigenesis of cervical cancer via inducting autophagy." (PMID 35456441, 2022). "ANXA6 acts as a tumor suppressor in cervical cancer via autophagy induction in vitro and in vivo." (PMID 36247003, 2022). "Nuclear ANXA6 expression has been proposed as a protein marker for squamous cervical cancer diagnosis, which may improve cervical cancer diagnosis at early stages and patient monitoring." (PMID 36247003, 2022). "Next, we analyzed the expression levels of ANXA6 in human cervical cancer." (PMID 33135350, 2020).
cervical cancer (continued). "ANXA6 downregulation is involved in human cervical cancer and may serve as a potential biomarker for the diagnosis, treatment, and prognosis of cervical cancer." (PMID 33135350, 2020). "Besides, ANXA6 expression levels may serve as a predictive biomarker of survival for cervical cancer patients." (PMID 36247003, 2022). "Thus, it is important to investigate the role of autophagy in ANXA6‐mediated cervical cancer." (PMID 33135350, 2020). "To evaluate the clinical importance of ANXA6‐induced autophagy in cervical cancer, we analyzed the correlation between ANXA6 and LC3 expression levels in human cervical cancer specimens." (PMID 33135350, 2020).
triple-negative breast carcinoma (11 papers, 2013 to 2026). An invasive breast carcinoma which is negative for expression of estrogen receptor (ER), progesterone receptor (PR), and human epidermal growth factor receptor 2 (HER2). "We previously demonstrated that lapatinib resistance in triple-negative breast cancer (TNBC) cells is associated with AnxA6 upregulation and accumulation of cholesterol in late endosomes." (PMID 42274606, 2026). "In spite of the intense interest in understanding the role of AnxA6 in cancer, the mechanisms underlying its contribution to triple negative breast cancer (TNBC) cell growth versus tumor cell adhesion and motility have remained elusive." (PMID 30719209, 2019). "In this study, we established the tumor suppressor function of AnxA6 in triple negative breast cancer (TNBC) cells by showing that loss of AnxA6 is associated with early onset and rapid growth of xenograft TNBC tumors in mice." (PMID 30719209, 2019). "Yet, AnxA6-dependent cooperativity of growth factors and lipoproteins may only occur in certain cells, as tyrosine kinase inhibitor treatment of triple-negative breast cancer cells caused AnxA6 upregulation and was associated with LE-Chol accumulation, possibly contributing to drug resistance." (PMID 35022465, 2022). "Exosomal ANXA6 from gemcitabine-resistant cells induced gemcitabine resistance in sensitive triple negative breast cancer (TNBC) cells, at least by downregulating EGFR." (PMID 36247003, 2022). "Here, we assessed the effect of hypoxia (1% Oxygen) on the tumor suppressor Annexin A6 (AnxA6) and the response of triple-negative breast cancer (TNBC) cells to epidermal growth factor receptor (EGFR) and androgen receptor (AR) targeted therapies." (PMID 36230969, 2022). "ANXA6 antitumor role may be more relevant in TNBC than in non-triple negative breast cancers." (PMID 36247003, 2022).